CD4 (CD4 molecule)
Diseases named in the same sentence as CD4 in open-access papers (continued):
Sharing a sentence is not in itself a finding about the gene and the disease.
infection (continued). "IL-2+ CD4+ T cells, especially IL-2+ CD4+ TCM cells, in the lung after infection were significantly associated with the vaccine-induced protection, whereas stronger IL-10 response and lower IL-2+ CD4+ T cells also contributed to the inferior protection of the DDA/TDB adjuvanted CMFO subunit vaccine." (PMID 33117374, 2020). "To determine whether TF variants preferentially carried Env with enhanced function we determined whether Envs varied in TZM-bl entry efficiency, binding to DC-SIGN and trans-infection of CD4+ cells." (PMID 31978062, 2020). "By measuring T cell responses in 29 individuals with either WN virus disease or asymptomatic infection, we showed that CD4 T cells focus on peptides in specific structural elements of C and at the exposed surface of the pre- and postfusion forms of the E protein." (PMID 32038660, 2020). "Whether HIV antigens are similarly degraded and displayed by CD4 T cells after latency reversal or during initial infection is unknown." (PMID 32196533, 2020). "After 3- and 7-days post-infection (dpi), we sorted cDCs from the LGs and co-cultured them with naïve CD4+ T cells in order to evaluate if cDCs could induce T cell proliferation." (PMID 32903439, 2020). "The small difference in baseline CD4+ cell counts between treatment groups is likely to reflect the trend in recent years to starting ART at earlier stages of infection, as evidence emerged of improved clinical outcomes and reduced transmission, which coincided with the increased use of INSTIs." (PMID 32516283, 2020). "CD4 cells (also known as CD4+ T cells) are white blood cells that fight infection." (PMID 33777501, 2020). "Therefore, to evaluate ADCP of HIV-1 infected cell, we replaced the cell line by primary blood CD4+T cells that are smaller than the monocytes and reach an infection range of 10–40% of the total target cell population upon ex vivo infection with HIV-1." (PMID 32582208, 2020). "A recent in vivo study using retroviral vector delivery of NullBasic to primary human CD4+ T cells and engraftment in a NSG mouse model demonstrated undetectable viral RNA in plasma samples up to day 14 post-infection and significantly reduced viral RNA levels in tissue-derived CD4+ T cells." (PMID 32923412, 2020). "• Splenic CD11chiMHCIIhi cDCs collected at days 21 and 28 post-infection express high IL-27 levels. • The DC-derived IL-27 may enhance the IFN-γ+ IL-10+ CD4+ cell polarization in vivo." (PMID 32849534, 2020). "Meanwhile, in some inflammation or infection context, CD4+ TRM cells play a crucial role and may persist in the skin for an extended period." (PMID 33633737, 2020). "Notably, the amount of [18F]FB-IL-2 uptake in the joints of FTY720-treated mice were limited to basal levels (2% ID/g), indicating that treatment inhibited the infiltration of activated CD4+ T cells into the infection site." (PMID 32477364, 2020). "Additionally, CD4+ LTi cells changed their distribution between 30 and 60 days of infection, as observed by histo-cytometry." (PMID 32351510, 2020). "Infection with the N74D CA mutant can be rescued by TRIM34 knockout in CD4+ T cells." (PMID 32282853, 2020). "The presence of a very high abundance of Salmonella-specific cytokine-producing CD4+ T cells in the intestinal lamina propria of V+I animals in our study suggests that they also play a vital role in the mucosal immune response against STM infection in the pig." (PMID 33584671, 2020). "Although, it cannot be excluded that the persistent infection of CD4 T cells could be intrinsic to CD4 T cells in which more than 98% of viral DNA is defective, additional cells could participate in this vicious cycle, feeding new infections." (PMID 31723251, 2020). "Many studies on intracellular pathogens have shown that the simultaneous production of IFN-γ, IL-2, and TNF-α by multifunctional CD4+ T cells may correlate with protection from infection." (PMID 33105734, 2020).
infection (continued). "The best-described viral reservoirs are resting CD4+ T lymphocytes, including central memory T lymphocytes, transitional T lymphocytes, and effector memory T lymphocytes, which maintain the infection by homeostatic proliferation in central memory and transitional memory T lymphocytes." (PMID 32670889, 2020). "The infection may be latent in CD4dimCD8bright T cells because they express β-catenin which induces de novo expression of CD4 on CD8+ T cells on hand and inhibits HIV at the transcriptional level at the other." (PMID 32960910, 2020). "Interestingly, infection rates for CD4-Ig (IC80) remained above 4% for two of three replicates even after the concentration was increased to 70 μg/mL after the fifth cycle." (PMID 32690692, 2020). "Therefore, in order to prevent surgical site infection, it is necessary to control the patient’s CD4 count and improve the patient’s immunity status." (PMID 33243159, 2020). "This process involves the CD8α+ DCs, which through TLR9-dependent recognition of the mtDNA (released from dead neutrophils) release IL-12p70, which generates FoxP3+Tregs from conventional CD4+T cells during a high dose infection, whereas a low dose infection induces CD8+T cell generation." (PMID 33643304, 2020). "During early infection, CD4+ T lymphocytes are the major target cells." (PMID 32670889, 2020). "In secondary infection, mice with NK cells depletion displayed significantly reduced type 1 T cell immunity, however inversely increased Tregs response as well as IL-4 production by CD4+ T cells." (PMID 32626664, 2020). "We included patients with active TB to test the reverse of our primary hypothesis: Once immunological control is lost over asymptomatic LTBI infection, active TB fuels CD4 depletion, weakens the immune system, and increases susceptibility to other diseases." (PMID 33284802, 2020). "RAG2−/− mice infected with Leishmania major demonstrated susceptibility to infection due to the absence of CD4+ T lymphocytes." (PMID 32867857, 2020). "As a negative control, naïve CD4+ T cells, which are poorly susceptible to infection by F4.HSA due to their low fusogenicity with CCR5-tropic HIV-1, were also sorted." (PMID 32353080, 2020). "HIV latency may be established through infection of actively dividing cells that revert to a resting state or direct infection of resting CD4+ T cells." (PMID 31852782, 2020). "At day 3 post infection we observed increased percentage of CD4 T cells." (PMID 31993218, 2020). "Second, the central role that CD4+ T cells play in the adaptive immune response suggests that CEACAM1 binding may suppress development of an adaptive response to the infection." (PMID 32582133, 2020). "Instead, if naïve CD4+ T cells are recruited that differentiate into Th2 cells it will be interesting to determine if their TCR repertoire differs from Th1 cells generated early in infection." (PMID 32655568, 2020). "Radar plots at 24, 48 and 72 hpi showed the equivalent TW10, ISW9 and KF11 peptides displayed by HIV-infected CD4 T cells along the infection rates (GFP+p24+) and MHC-I levels of the same LRA-treated HIV-infected CD4 T cells scaled to the maximum value of each parameter across time points." (PMID 32196533, 2020). "In addition, transient CD8+ T-cell depletion in vaccinated rats resulted in prolonged infection, followed by clearance within 84 weeks, while CD4+ T cell depletion resulted in development of chronic infection, with viremia lasting at least 126 weeks." (PMID 32485887, 2020). "Macrophages generally maintain long-term infection, while CD4+ T cells most often are effectors of the acute lytic infection, which may explain the differences." (PMID 33266347, 2020). "TEM and TFH cells displayed most of these RU-5 transcripts, which may be indicative of recent infection of these CD4 T cells in both compartments." (PMID 31723251, 2020).
infection (continued). "M. tuberculosis possesses antigens that are recognised by FoxP3+CD4+ regulatory T cells, which expand in patients with an active infection and act to suppress the effector T cell responses against the bacterium, enabling the infection to expand and prolonging the bacterial burden." (PMID 32858901, 2020). "However, during the course of infection, the frequency of IFNγ-secreting CD4+ T cells was similar in both groups." (PMID 33375150, 2020). "The increased bacterial burdens and subsequent mortality led us to speculate that the CD4 T cell response was blunted in thymectomized mice, which prevented control of the infection." (PMID 32722409, 2020). "To note, in vivo labelling of CD45+ cells were performed in wt mice at day 4 post re-infection to distinguish T cells residing in the vasculature versus in the lung parenchyma and a majority (70–80%) of the CD4+ and CD8+ T cells were shown to reside in the lung parenchyma." (PMID 33123150, 2020). "In addition, infection with L. infantum significantly induced the development of IFN-γ-producing CD4+ T cells, in terms of both percentage and total cell number, in both the WT and Irf1−/− mice compared to their counterparts." (PMID 32210480, 2020). "Interestingly, at 24 h post-infection, the Trivalent-FP induced IL-22-producing CD4+ T cells in the WT group as well, suggesting that the IL-22 production is not controlled by the human-FcγRI." (PMID 32340134, 2020). "In a colony of experimentally FIV-infected cats, we determined that the latent reservoir in peripheral CD4+T cells during the asymptomatic phase of FIV-C infection to be approximately one in 105 cells (that is, 1 in 103 cells is infected, but only 1 in 102 of those is replication competent)." (PMID 32380756, 2020). "Mice were euthanized on days 3, 5, 7, 14, 21, and 32 post-infection, and the 2W-specific CD4+ T cell response was assessed in the SLOs, liver, and blood using flow cytometry following enrichment for Ag-specific CD4+ T cells using 2W:I-Ab tetramer and magnetic bead technology." (PMID 32983171, 2020). "We assessed the antigen-specific CD4+ T cell and B cell responses on day seven post-infection." (PMID 32407154, 2020). "The preferential infection of CD4+ T-cells is clearly supported by studies of infected humans and NHPs in which the frequency of CD4+ T-cells containing viral DNA, RNA, or protein is high relative to the low frequency found in monocytes in the blood or myeloid cells in tissues." (PMID 32992787, 2020). "However, in the TCS exposed mice the frequency of CD4+ T cells was reduced at the site of infection and proximal to the site of infection, with significant reductions seen in the BAL, lung, and LLNs compared to the VC/PR8 mice." (PMID 33373420, 2020). "As expected, at day 50 or 99 post infection we could only stimulate cytokine expression in uGT CD4 cells taken from both vaccinated/infected animals." (PMID 31993218, 2020). "Interestingly, DCs have also been shown in in vitro and ex vivo settings, to increase the infection of CD4+ T lymphocytes through cis-infection and trans-infection mechanisms." (PMID 32181159, 2020). "Activated CD4 T cells appear within three days of infection and peak one week after infection." (PMID 32727077, 2020). "Importantly, we provide for the first time a full picture of the cascade of splicing events and the crosstalk between splice sites that shapes viral RNA landscape during the early steps of infection in primary CD4+ T cells." (PMID 32807178, 2020). "The percentage of CD4 T cells also peaked around day 14 post infection." (PMID 31993218, 2020). "This binding and/or internalization of HIV-1, with limited infection of DCs, increases CD4+ T cell infection in vitro and may involve immunological synapse formation (contact zone between DCs and CD4+ T cells) thereby polarizing HIV-1 delivery to CD4+ T cells." (PMID 32181159, 2020). "This suggests that macrophages amplify infection in other cell types, most notably CD4+ T cells." (PMID 32726944, 2020).
infection (continued). "Therefore, we sorted virus-specific TFH cells and TH1 cells from the SMARTA chimeric mice on day 2 after the LCMV Armstrong infection and naïve CD4+ T cells (CD4+CD25−CD62L+CD44−) from naïve mice and subsequently performed H3K27me3 ChIP-Seq experiments." (PMID 30842630, 2020). "Astrocytes lack expression of the critical CD4 molecule that facilitates the infection of lymphocytes, microglia and macrophages but yet they have been shown to be susceptible to HIV and viral DNA and viral protein has been detected in post-mortem brain tissue from HIV+ patients." (PMID 32650790, 2020). "Therefore, we quantified different CD4+ T cell subsets based on their signature cytokine production in our experimental groups at 60 days post infection." (PMID 32437421, 2020). "However, resolution of infection is increased or more rapid in the presence of CD4+ T cells both for E. chaffeensis and for E. ruminantium." (PMID 33233869, 2020). "The help provided by CD4+ T cells promotes somatic hypermutation and enables antibody class switching, allowing for the generation of high affinity antibodies of the most effective isotype for the given infection." (PMID 33374787, 2020). "Moreover, infection-elicited CD4+ responses were superior than vaccine-elicited responses for influenza A/H1N1 (931 vs 1; p = 0.026), A/H3N2 (647 vs 1; p = 0.041) and B (619 vs 1; p = 0.004)." (PMID 32572168, 2020). "It is possible that CD4+ T cells may be strongly activated earlier during the infection and then revert to the quiescent state after providing helper functions, which could explain the undetected activated phenotype." (PMID 32975374, 2020). "While antibodies produced in response to the vaccine may provide some modest protection against infection, we determined that in our infection model, CD4+ T cells are critical for vaccine-induced protection." (PMID 32817694, 2020). "Importantly, however, the ratios of integrated HIV DNA to productive infection rates as defined by HSA expression were always disproportionately higher in the CD127+ Tm cells than in the other two subsets of memory CD4+ T cells." (PMID 32353080, 2020). "The cluster A region was first described as the binding site for CD4-inducible (CD4i) antibodies isolated from natural infection that competed for binding to the CD4-triggered gp120 with mAb A32 or C11, two antibodies isolated from infected individuals in the early 90s." (PMID 32605979, 2020). "In addition, phagocytosis of infected CD4+ T cells by macrophages leads to greater infection of macrophages than does incubation with cell-free virus." (PMID 32726944, 2020). "However, vervets can partially restore CD4+ T cells in the gut during the chronic stage of infection." (PMID 33158452, 2020). "This review will discuss the antigen specificity, effector function, phenotype and direct anti-viral properties of HCMV specific CD4+ T cells, as well as reviewing our understanding of the importance of this T cell subset in primary infection and long-term carriage in healthy individuals." (PMID 32509591, 2020). "Immune cells were isolated from peripheral blood (PBMCs) and the PP tissue (PP cells) within each intestinal segment at 28 days post-infection to analyze the frequency of T cells (CD4+, CD8+, γδ+), innate lymphoid cells (ILCs; CD335+) and myeloid cells (CD14+ and CD11c+)." (PMID 33329565, 2020). "Whether HIV epitope presentation is similar between latency reversal and initial infection of CD4 T cells is unknown yet crucial to define immune responses able to detect HIV-infected CD4 T cells after latency reversal." (PMID 32196533, 2020). "Since HIV-1 preferentially infects activated CD4 T cells, and since the reservoir is partly established early during infection when most of those cells are responding to HIV, many reservoir cells might be HIV-specific." (PMID 33228686, 2020).
infection (continued). "These interactions, although not leading to potent HIV-1 fusion/entry, are involved in trans-infection by presenting virions to CD4+ T cells; however, it has been proposed that the engagement of this CLRs also efficiently directs bound virions to endolysosomal compartment for degradation." (PMID 32181159, 2020). "Other bottlenecks to systemic infection spread may exist, and establishment of infection may be a two-step process, where resting CD4+ T cells are initially infected in the mucosa." (PMID 32017770, 2020). "Because the immunopathology is thought to be important during HCPS and the balance between protective and harmfully immune response is unknown, CD4+ T regulatory (Treg) response could play an important role during and to resolve infection." (PMID 32984065, 2020). "Since cytokine production by the CD4+ T cells upon in vitro restimulation was the only functional read out that we found significantly different, we propose that LAG-3 blockade is likely to act as a rapid and temporary boost of activated CD4+ T cells in this infection." (PMID 33519801, 2020). "The importance of intrinsic MyD88-dependent signals in promoting CD8 and CD4 T cell survival and initial proliferation was also demonstrated in in vivo studies in various models of infection, including Toxoplasma gondii and Lymphocytic choriomeningitis virus (LCMV) infections." (PMID 32547564, 2020). "The metabolic environment for HIV protein expression and degradation differs drastically between productive infection in activated CD4 T cells and latency reversal in differentiated resting CD4 T cells, but the consequences on the degradation machinery and epitope production are not known." (PMID 32196533, 2020). "Alternatively, intact proviruses could form more efficiently in TN cells; however, a recent study suggests greater than 90% of proviruses are intact after a single-round infection of primary CD4+ T cells, making this hypothesis less likely." (PMID 33055422, 2020). "We did observe that the severe impairment of CD4+ T cells in the early period of CRO infection was correlated with death, therefore, therapy that reverses T cell exhaustion may restore host immunity of patients and improve their survival." (PMID 33072617, 2020). "This case is interesting since there are very few studies on patients with mild infections and because IgM and IgG antibodies, antibody secreting B cells, CD4 TFH cells, and activated cytotoxic CD8 cells were shown to be circulating before resolution of the symptoms." (PMID 32612615, 2020). "Indeed, CD4+ T cells from day 15 of infection exhibited ECAR that was only modestly increased compared with resting CD4+ T cells from naive mice." (PMID 32817333, 2020). "BaL Env is macrophage tropic, has a Tier 1 phenotype and requires little CD4 to support infection." (PMID 33101312, 2020). "However, specific players such as CD4 T cell loss and TME heterogeneity in infection and cancer, respectively, contribute to define distinct and overlapping traits of exhausted T cells in the two conditions." (PMID 32714330, 2020). "It has been shown that rapidly recruited, pre-existing CD4+Ly6C+T effector cells that are short-lived in the absence of infection, mediate concomittant immunity at the site of secondary infected sand fly challenge, in mice with a chronic primary infection." (PMID 32176691, 2020). "Furthermore, CXCR3 receptor was highly expressed on the surface of CD4+ Foxp3+ cells during infection when compared to naïve cells." (PMID 32574175, 2020). "In acute-resolving infection, these CD4+ T cell responses are maintained." (PMID 32781731, 2020). "At 2 weeks post infection following needle inoculation in the ear, Axl-/-Mertk-/- mice showed significanly decreased IL-10 production from both CD4+ and CD8+ T cells which was accompanied by increased frequencies of IFNγ and iNOS expression from CD4+ T and myeloid cells, respectively." (PMID 33137149, 2020).